APLN (apelin)
Diseases named in the same sentence as APLN in open-access papers (continued):
Sharing a sentence is not in itself a finding about the gene and the disease.
atrial fibrillation (continued). "Further studies could focus on the predictive effect of apelin in the morbidity of atrial fibrillation and the possibility of maintaining a sinus rhythm." (PMID 29302260, 2017). "Based on the existing studies concerning apelin and atrial fibrillation, the level of apelin in patients with AF may reflect the systolic function of the atrium." (PMID 29302260, 2017). "Additional research is needed to verify whether apelin could be used in clinical practice to rule out atrial fibrillation and to improve AF screening in patients with increased risk of ischemic stroke." (PMID 34712712, 2021). "Thirdly, apelin levels may change during the natural history of atrial fibrillation and our study did not follow changes of apelin levels over time." (PMID 34712712, 2021). "We believe that our results encourage further research of apelin as a biomarker that might be used to rule out atrial fibrillation." (PMID 34712712, 2021).
ischemic stroke (17 papers, 2015 to 2026). A stroke disorder caused by obstruction of blood flow to the brain, due to thrombotic (local blood clot formation) or embolic (due to a blood clot or other material traveling from another site) event. "The apelin/APJ system is closely associated with the pathogenesis of ischemic stroke, which is currently the most common cerebrovascular disease." (PMID 36034795, 2022). "Therefore, the temporal expression of apelin/APLNR in ischemic stroke and the underlying mechanisms need to be further investigated, which is crucial for the therapeutic application of apelin or APLNR agonists to treat ischemic stroke." (PMID 28167898, 2017). "Apelin-13 has been shown to be beneficial in aortic calcification, ischemic stroke, and subarachnoid hemorrhage by alleviating ER stress." (PMID 37723076, 2023). "Apelin-13 attenuated ER stress-mediated the cerebral infarct and neuronal apoptosis in ischemic stroke." (PMID 37008060, 2023). "AMPK signaling was also reported to participate in the antiapoptotic role of apelin-13 in ischemic stroke." (PMID 36902176, 2023). "Exogenous apelin-13 supplementation in ischemic stroke patients can play a neuroprotective role by regulating multiple signaling pathways." (PMID 36034795, 2022). "Secondly, novel APJ receptor agonists or antagonists have to be developed to verify the feasibility and efficacy of the apelin-13/APJ system as an intervention target in ischemic stroke." (PMID 36034795, 2022). "Growing evidence indicates that the apelin/APJ system is involved in the pathophysiology of ischemic stroke." (PMID 32194492, 2020). "In this review, we sum up the latest research progress relating to the actions and therapeutic potential of the apelin/APJ system in ischemic stroke." (PMID 32194492, 2020). "Meanwhile, the specific effect of apelin on oxidative/nitrosative stresses in ischemic stroke remains to be further determined." (PMID 32194492, 2020). "The expression of the apelin/APJ system components in different stages of ischemic stroke is temporally altered." (PMID 32194492, 2020). "The apelin/APJ system can inhibit inflammatory responses after ischemic stroke via reducing the generation of inflammatory mediators." (PMID 32194492, 2020). "Further intensive study and repeated validation of the relationship between gene polymorphism of apelin/APJ system and ischemic stroke can predict the risk of ischemic stroke, which will provide strategies for prevention and treatment of ischemic stroke." (PMID 32194492, 2020). "An in-depth knowledge of the pathophysiological effects of the apelin/APJ system and the underlying mechanisms will help to develop novel therapeutic interventions for ischemic stroke." (PMID 32194492, 2020). "In this review, we mainly focus on the latest research progress related to the biological functions and therapeutic potential of the apelin/APJ system in ischemic stroke." (PMID 32194492, 2020). "In the model of ischemic stroke, the apelin-13/APJ system suppressed the activation of microglia and astrocyte and reduced neutrophil infiltration." (PMID 31791369, 2019). "Here, we first reported that low dose of apelin-36, other than apelin-13, administrated after ischemic stroke significantly reduced infarct volume in rats." (PMID 29085332, 2017). "In this study, we first reported that low dose of apelin-36, other than apelin-13, administrated after ischemic stroke significantly reduced infarct volume in rats." (PMID 29085332, 2017). "A growing body of evidence indicates that the apelinergic system, consisting of apelin and apelin receptor (APLNR), is implicated in ischemic stroke." (PMID 28167898, 2017). "Blocking this vicious cycle by suppressing oxidative stress is a major mechanism of apelin/APLNR’s protective effects on ischemic stroke." (PMID 28167898, 2017).
ischemic stroke (continued). "In the current study, we first investigated the therapeutic effect of apelin-36 and apelin-13 on ischemic stroke by administrating low dose of apelin-36 or apelin-13 after ischemic stroke." (PMID 29085332, 2017). "It highly suggested that low dose of apelin-36, other than apelin-13, has protective effect on ischemic stroke." (PMID 29085332, 2017). "Our data support the therapeutic potential of apelin-36 in ischemic stroke although further investigation is needed." (PMID 29085332, 2017). "Preventive administration of apelin-13 or apelin-36 was applied in the majority of studies of ischemic stroke, which only indicated that apelin-13 or -36 has a preventive effect on protecting brains from I/R injury." (PMID 29085332, 2017). "We explored the noninvasive intranasal brain delivery method and investigated therapeutic effects of apelin-13 in a focal ischemic stroke model of mice." (PMID 26391329, 2015). "In seeking for a noninvasive method to deliver apelin as a clinically feasible treatment for ischemic stroke, the intranasal route is an attractive and practical method." (PMID 26391329, 2015). "Interestingly, previous studies reported that ER stress was a critical regulator of apelin-mediated protective effects in ischemic stroke, diabetes and heart failure." (PMID 37723076, 2023). "Another report suggests that intranasal delivery of Apelin-13 could promote angiogenesis and elicit neuroprotective effects after ischemic stroke in mice, indicating that Apelin can promote angiogenesis." (PMID 35725619, 2022). "Given that moyamoya disease has better collateral circulation compared to ischemic stroke, high plasma levels of apelin may be indicative of good collateral circulation." (PMID 36034795, 2022). "Finally, the injection route, injection time and treatment frequency of apelin-13 in pre-clinical studies need to be optimized before clinical studies on ischemic stroke patients." (PMID 36034795, 2022). "However, the specific effects of the apelin/APJ system on other types of ischemic stroke are rarely reported." (PMID 32194492, 2020). "Apelin heals ischemic strokes by inhibiting cell death and increasing angiogenesis." (PMID 31067839, 2019). "Furthermore, apelin-13 attenuates microglia recruitment and activation, contributing to the reduction of inflammatory cytokines and the alleviation of inflammation in ischemic stroke." (PMID 29085332, 2017). "The later-stage reduction of apelin and APLNR may be associated with a plethora of mechanisms in ischemic stroke." (PMID 28167898, 2017). "Accumulated evidence suggests that low dose of apelin-36 may have therapeutic effect on ischemic stroke; meanwhile, it may have less side effect." (PMID 29085332, 2017). "It suggested that the inhibitory effect of apelin-36 on cellular apoptosis in ischemic stroke may be mediated by the suppression of ERS/UPR." (PMID 29085332, 2017). "It suggested that apelin-36 may also inhibit cerebral I/R injury-induced inflammation by attenuating microglia recruitment and activation, contributing to the protective effect of apelin-36 on ischemic stroke." (PMID 29085332, 2017). "The results suggest that apelin-13 could be used as a neuroprotective as well as a regenerative treatment after ischemic stroke." (PMID 26391329, 2015). "Thesefindings indicated that enhanced VEGF and Apelin/APJ might play roles inangiogenic effects of HUK in ischemic stroke." (PMID 26222055, 2015). "However, the role of apelin-36 in ischemic stroke is less studied." (PMID 29085332, 2017). "We found that apelin-36 significantly reduced cerebral I/R injury-induced cellular apoptosis in the cortex, suggesting that apelin-36 may inhibit both neuronal apoptosis and astrocyte apoptosis in ischemic stroke." (PMID 29085332, 2017). "However, the therapeutic effect of apelin-13 and apelin-36 on ischemic stroke remains elusive." (PMID 29085332, 2017).
ischemic stroke (continued). "Thus, apelin administration may block this vicious cycle to inhibit ER stress-induced apoptosis in ischemic stroke." (PMID 28167898, 2017). "In addition, PI3K/AKT and ERKs signaling pathways play a crucial role in apelin/APLNR-induced angiogenesis in ischemic stroke, which may be mediated by VEGF-VEGFR2." (PMID 28167898, 2017). "Recently, numerous studies show that the apelin/APJ axis possesses neuroprotective effects by inhibiting neuronal apoptosis and improving functional recovery through diverse pathways in ischemic stroke." (PMID 32194492, 2020). "In this study, ischemic stroke was induced through MCAO and reperfusion (MCAO/R) operation in rats, and Apelin 13 was given intracerebroventricularly 15 min before reperfusion followed by chronic treatment of daily administration for 3 days." (PMID 30709405, 2019). "In this review article, we summarize the temporal expression of apelin and APLNR in ischemic stroke and the mechanisms of their dysregulation." (PMID 28167898, 2017). "Accumulated evidence indicates that the apelinergic system, consisting of apelin and apelin receptor (APLNR), is temporally dysregulated in ischemic stroke." (PMID 28167898, 2017). "On the contrary, the expression of VEGF in cultured endothelial cells is partially suppressed by the apelin/APJ system inhibitor, suggesting that the apelin/APJ system may cooperate with VEGF to promote vascular growth in ischemic stroke." (PMID 32194492, 2020). "The apelin/APJ system is widely distributed in the central nervous system, participating in many pathophysiological regulations of some brain diseases, including ischemic stroke." (PMID 32194492, 2020). "Up to now, there is no report about the role of apelin/APJ signaling in autophagy in ischemic stroke." (PMID 32194492, 2020). "Therefore, we summarize the temporal expression of apelin and APLNR in ischemic stroke, the mechanisms of their dysregulation, the protective effect of the apelinergic system on ischemic stroke and the underlying mechanisms of its protective effect." (PMID 28167898, 2017). "Recent studies indicate that the expression of apelin and APLNR may be temporally regulated in ischemic stroke." (PMID 28167898, 2017). "For example, apelin significantly reduces the expression of inflammatory cytokines in rat brains, such as interleukin 1 beta (IL-1β), TNF-α and intercellular adhesion molecule 1(ICAM-1), and inhibits cell apoptosis in rats with ischemic stroke." (PMID 28167898, 2017). "Moreover, the expression of apelin and APLNR is temporally dysregulated during different phases of ischemic stroke." (PMID 28167898, 2017). "For the first time, apelin-13 was shown to promote the angiogenesis and LCBF restoration after ischemic stroke, indicating the potential application of apelin-13 as a multifaceted drug for acute and chronic treatments of ischemic stroke." (PMID 26391329, 2015). "Moreover, no study has compared the differential effect of apelin-13 and apelin-36 on ischemic stroke." (PMID 29085332, 2017).
lung cancer (17 papers, 2016 to 2024). A malignant neoplasm involving the lung. "Increased Apelin protein level is associated with elevated microvessel densities and predicts poor overall survival, suggesting Apelin as a novel angiogenic factor in human lung cancer cell." (PMID 27733135, 2016). "Apelin (APLN), a tumor promoter in tumors, inhibits lung cancer cell proliferation by suppressing exosomal miR-15a-5p expression, suggesting that exosomal miR-15a-5p has a tumor suppressor function." (PMID 38892270, 2024). "APLN expression levels inversely correlate with overall survival in breast, colorectal, and lung cancer by directly correlating with increased angiogenesis in these tumors." (PMID 32545380, 2020). "In murine lung cancer models, apelin knockout reduced tumor burden and prolonged survival by inhibiting VEGF, TGF-β1, and TNF-α and simultaneously decreased MDSC infiltration in the TME." (PMID 33469537, 2020). "In both breast and lung cancer, we found that the combination of Apelin inhibition with sunitinib, an anti‐angiogenic therapy used in patients, resulted in potent reduction of tumor growth and angiogenesis." (PMID 31267692, 2019). "We detected the expression levels of apelin and miR‐195 in lung adenocarcinoma tissues and lung cancer cell lines using Western blotting and quantitative reverse transcription PCR assay, respectively." (PMID 31070305, 2019). "Knockout of Apelin resulted in enhanced survival and reduced tumor burden in these lung cancer models (Fig EV1F–H)." (PMID 31267692, 2019). "It has been proved that apelin plays an important role in angiogenesis in lung cancer." (PMID 33912466, 2021). "Thus, high Apelin levels correlate with a worse prognosis in breast and lung cancer patients, and Apelin inactivation increases the survival of mice with breast and lung cancer." (PMID 31267692, 2019). "Thus, we conclude that Apelin is the primary Apelin receptor ligand upregulated in our models of mammary and lung cancer." (PMID 31267692, 2019). "Up-regulation of APLN has been shown in brain 33, colon 34, gastroesophageal 35 and lung cancers." (PMID 31410213, 2019). "Apelin was expressed in cultured lung cancer cell lines both at the mRNA and protein levels." (PMID 27733135, 2016). "In human non‐small cell lung cancer (NSCLC) specimens, APLN expression correlates positively with capillary size and microvessel density (MVD)." (PMID 39434201, 2024). "Recently, APLN/APLNR was shown to be involved in several kinds of cancers, such as lung cancer, gastroesophageal cancer, colonic cancer, and hepatocellular carcinoma." (PMID 36193059, 2022). "Expression and role of apelin/APJ signaling in gastric cancer, gastroesophageal cancer and lung cancer." (PMID 33912466, 2021). "In this issue of EMBO Molecular Medicine, Uribesalgo and coworkers show that high Apelin expression correlates with poor survival in advanced breast (MMTV‐NeuT) and lung (KRASG12D) murine tumor models as well as in breast and lung cancer in humans." (PMID 31318171, 2019).
preeclampsia (17 papers, 2018 to 2025). Preeclampsia is a hypertensive disorder of pregnancy that is characterized by new-onset hypertension with proteinuria presenting after 20 weeks of gestation, and depending on mild or severe forms may initially present with severe headache, visual disturbances, and hyperreflexia. "Despite these inconsistencies, there are indications of an association between apelin concentrations and preeclampsia." (PMID 39457235, 2024). "It is estimated that preeclampsia occurs in 3–7% of pregnancies and that it is associated with decreased plasma apelin concentrations." (PMID 37964253, 2023). "This study aimed to explore the effects of apelin-13 administration on preeclampsia-associated renal dysfunction and proteinuria." (PMID 33850656, 2021). "Preeclampsia modulates the apelinergic system, causing an increase in apelin in the stroma and on the trophoblastic surface." (PMID 34577885, 2021). "The ROC analyses revealed that apelin has poor reliability as a diagnostic tool in the exclusion of preeclampsia—sensitivity (61–64%) and specificity (61–73%, AUC (0.63–0.67))." (PMID 33321877, 2020). "Because preeclampsia is associated with higher levels of sFlt-1 and vasopressin, we tested the effects of systemic (Pyr1)-apelin-13 administration on these circulating markers." (PMID 31189936, 2019). "The potential molecular mechanism of apelin activity and its contribution to the development of preeclampsia may be elucidated via the effects caused by the stimulation of its cellular receptors." (PMID 33321877, 2020). "As described in paragraph 6.3, several adipokines, such as adiponectin, leptin, resistin, visfatin and apelin, are also secreted by the placenta and have been implicated in metabolic adaptations to normal gestation, as well as in preeclampsia and other complications of pregnancy." (PMID 31505789, 2019). "However, apelin provision in preeclamptic rats (PE + apelin) significantly decreased the elevated systolic, diastolic, and mean arterial blood pressures and reversed the PE-associated proteinuria indicating amelioration of preeclampsia symptoms." (PMID 34819954, 2021). "A study published in 2023 showed that serum apelin concentration increased in pregnant women with preeclampsia, but APJ expression decreased in preeclamptic placentas." (PMID 41523861, 2025). "Different studies show that serum apelin levels of pregnant women with preeclampsia are lower, higher, or similar to those of normotensive pregnant women." (PMID 41523861, 2025). "Molecular examination of the placentas revealed that the Apelin/APJ system protects trophoblasts from hypoxia-induced oxidative stress by activating the PI3K/Akt signaling pathway in preeclampsia." (PMID 41523861, 2025). "As a result, apelin plays a significant role in fetal growth disorders, preeclampsia, and obesity-related disorders." (PMID 39457235, 2024). "An interesting study separately evaluated the serum concentrations of the most bioactive apelin peptide fragments, namely, apelin-13 and apelin-36, in preeclampsia patients with the aim of exploring their potential association with perinatal morbidity." (PMID 39457235, 2024). "With regard to preeclampsia, it was observed that apelin administration in these cases resolves villous edema and irregularity in cell arrangement." (PMID 39457235, 2024). "The value of apelin in preeclampsia treatment was validated via numerous reports of its pleiotropic effects on the inhibition of inflammation, angiogenesis, vasodilation, and oxidative stress." (PMID 39457235, 2024). "In animal studies, apelin significantly improves preeclampsia symptoms, impairs endothelial nitric oxide synthase/nitric oxide signalling, and has a positive impact on oxidative stress activation." (PMID 38203346, 2023).